IL6 (interleukin 6)
Diseases named in the same sentence as IL6 in open-access papers (continued):
Sharing a sentence is not in itself a finding about the gene and the disease.
metabolic syndrome (continued). "Of note, in relation to diet, IL-6 is also associated with the development of metabolic syndrome and cardiovascular disease in patients with RA, as demonstrated by the administration of IL-6 inhibitor, tocilizumab, leading to a subsequent increase in insulin sensitivity." (PMID 33076469, 2020). "Moreover, the correlation between IL-6 deficiency and dyslipidemia is challenged by one group reporting that IL-6 treatment is the causative factor of dyslipidemia." (PMID 30134607, 2018). "Furthermore, a reduction of IL-6 levels can significantly improve the metabolic syndrome, also considered a risk factor of OA." (PMID 28846633, 2017). "Faecal calprotectin is regularly used as indicator for the main inflammatory bowel diseases (IBD) such as Crohn’s disease and ulcerative colitis, meanwhile TNF-α and IL-6 are proinflammatory cytokines which have been linked with abdominal obesity and the metabolic syndrome." (PMID 28335517, 2017). "Since IL-6 upregulation could be associated with high serum triglycerides, it could be suggested that metabolic syndrome in NE cases may contribute to proinflammatory cytokine activation, particularly IL-6." (PMID 28053993, 2016). "In NAFLD, oxidative stress may induce production of tumor necrosis factor-α and interleukin-6 and add atherogenic stimuli to the already high oxidative and proinflammatory status that is closely associated with metabolic syndrome." (PMID 26125952, 2015). "Furthermore, the major risks of ischemic stroke are within the scope of metabolic syndrome, and inflammatory cytokines including hsCRP, TNFα, and IL-6 have been proven to be significantly associated with the occurrence and outcomes of ischemic stroke." (PMID 24716192, 2014). "Future studies including this parameter and other relevant biomarkers linked to the metabolic syndrome, e.g. interleukin (IL)-6, tumour necrosis factor (TNF)-α and C-reactive protein (using high-sensitivity assays), should assist in further interpretation of the data obtained." (PMID 19575082, 2009). "Furthermore, the anti-inflammatory effects of ginger and lemon may contribute by downregulating pro-inflammatory cytokines such as TNF-α, IL-6, and NF-κB—key mediators implicated in both oxidative stress and dyslipidemia." (PMID 40938933, 2025). "In our study, IL-1β and IL-6 values also tended to be higher than in controls, and this confirms that survivors of childhood brain cancer may have a chronic inflammatory state that favors the onset of metabolic syndrome and cardiovascular risk." (PMID 38254811, 2024). "Moreover, our recent report has shown a strong association between gut microbiota alterations, dyslipidemia, increased serum indoxyl sulfate levels, heightened oxidative stress, and elevated serum IL-6 and MCP-1 levels, which together contribute to a high three-year CVD risk in patients with ESKD." (PMID 39457689, 2024). "The metabolic syndrome is associated with the occurrence of chronic inflammation that remains at a low level, which is characterised by the predominance of pro-inflammatory factors in the systemic circulation, e.g., IL-6 and TNFα and IL-18, which are involved in the pathogenesis of LUTS/BPH." (PMID 37847180, 2023). "We found that Amuc_1100 intervention significantly reduced the mRNA levels of Il6 in 3T3-L1 cells, demonstrating that Amuc_1100 inhibits inflammation-associated lipolysis and indicating that Amuc_1100 protects the body from metabolic syndromes and has less adverse effects." (PMID 36847500, 2023). "Moreover, increased plasma D-dimer was also found to be independently associated with an inflammatory state (assessed by IL-6) and dyslipidemia in T2D, which could contribute to nerve dysfunction and neuropathy." (PMID 36082076, 2022). "Low IL-10 levels might reinforce the IL-6 mediated risk of developing metabolic syndrome." (PMID 35135482, 2022).
metabolic syndrome (continued). "Taken together, current evidence indicates that IL-6 abnormality may lead to dyslipidemia which predisposes to cardiac lipotoxicity, although it remains unknown regarding which form (i.e., IL-6 excess or deficiency) is responsible and further research is required." (PMID 30134607, 2018). "Attenuation of pro-inflammatory cytokines such as IL-6, TNFα, and IL-1β secreted by immune cells and adipocytes may be a therapeutic approach for treating systemic low-grade chronic inflammation-associated with metabolic syndrome." (PMID 29592806, 2018). "In addition, our results showed that among smokers, CRP was associated with age while IL-6 was significantly associated with age, smoking variables as measured by years of smoking and number of pack-years, and dyslipidemia as measured by low HDL and high triglycerides levels." (PMID 26366318, 2015). "Increased IL-6 expression and circulating levels have been associated with a variety of diseases, including metabolic and vascular diseases, such as central obesity, the metabolic syndrome, type 2 diabetes mellitus, atherosclerosis and, in particular, atherosclerotic coronary artery disease." (PMID 20652043, 2010). "Serum IL-6 levels are elevated in obese individuals, as well as in patients with chronic inflammatory conditions and dyslipidemia, with adipose tissue contributing approximately one-third of circulating IL-6." (PMID 41562846, 2026). "A decrease in IL6 has been shown in patients with metabolic syndrome undergoing dietary intervention." (PMID 41190148, 2025). "Probiotics can also benefit the heart by decreasing TMAO, LDL-c, TG, CRP, MDA, TNF-α, IL-6, and urea levels, improving dyslipidemia and toxin profiles." (PMID 40913714, 2025). "These substances, including interleukin-6 (IL-6) and tumor necrosis factor-alpha (TNF-α), contribute to a state of chronic low-grade inflammation, a hallmark of metabolic syndrome and cardiovascular disease." (PMID 40217861, 2025). "The decline in estrogen further leads to elevated pro-inflammatory adipocytokines (TNF-α, IL-6), increased low-density lipoprotein (LDL), and heightened triglyceride levels, all of which elevate the risk of cardiovascular disease and metabolic syndrome (MetS)." (PMID 40469982, 2025). "Further, systemic inflammation, a feature of metabolic syndrome, can inhibit Apo-AI production via inflammatory cytokines such as IL-6 and TNF-alpha." (PMID 41361833, 2025). "Clinical and animal sample tests found that the levels of IL-6 in the serum of dust-exposed workers and mice, as well as in liver tissue, were significantly elevated in the dyslipidemia group." (PMID 40282416, 2025). "These processes are mediated through inflammatory cytokine activation, such as IL‐6, TNF‐α, TGF‐β1, and mitochondrial dysfunction, reinforcing the causal role of uric acid in dyslipidemia and cardiovascular disease." (PMID 41287972, 2025). "A key marker in this pathway is C-reactive protein (CRP), a liver-produced inflammatory biomarker triggered by interleukin-6 (IL-6) and other cytokines, and linked to elevated risk of CVD, metabolic syndrome, and related conditions." (PMID 40514590, 2025). "These macrophages secrete cytokines such as TNF-α and IL-6, exacerbating the inflammation eventually resulting in lipotoxicity, systemic inflammation and contributing to IR and metabolic syndromes." (PMID 41373779, 2025). "The effects of six weeks of moderate-intensity aerobic exercise supplemented with nano-curcumin on BDNF and inflammatory markers (IL-6 and IL-10) in patients with metabolic syndrome aged 60 to 65 years were also studied by Osali." (PMID 41228407, 2025). "Data have shown that fat-to-lean mass ratio correlates with both high-sensitivity C-reactive protein and interleukin-6 and is considered the strongest predictor of metabolic syndrome." (PMID 39982289, 2025).
metabolic syndrome (continued). "Chronic inflammation is a hallmark of metabolic syndrome, and anthocyanins (320 mg/day for 4 weeks) can lower systemic inflammation by inhibiting proinflammatory factors like TNF-α and IL-6, thus alleviating metabolic syndrome symptoms." (PMID 40626227, 2025). "Elevated levels of proinflammatory cytokines such as tumor necrosis factor-alpha (TNF-α) and interleukin-6 (IL-6) are common in individuals with metabolic syndrome." (PMID 41393278, 2025). "The association between psoriasis and dyslipidemia is predicated on Th1-cell activation, autoantibodies against oxidized LDL, and the influence of cytokines (TNF-α, IL-1, and IL-6)." (PMID 40370872, 2025). "Serum progranulin levels are significantly associated with inflammatory markers, including C-reactive protein and interleukin-6, and have also been shown to be positively correlated with components of metabolic syndrome." (PMID 41010769, 2025). "Our findings of increased levels of IL‐6 and hsCRP in individuals with AUD compared with individuals without AUD support the link between AUD and an increased risk of metabolic syndrome or CVD reported in previous studies." (PMID 40630018, 2025). "In metabolic syndrome, this is formed through the activation of macrophages and the release of IL-6, TNF-α, and other cytokines." (PMID 41375041, 2025). "In parallel, the Mediterranean pattern provides an intrinsic anti-inflammatory component: reductions in hs-CRP/IL-6 in metabolic syndrome, and even isocaloric CRP decreases (−26.1% in 5 weeks) without weight loss." (PMID 41305609, 2025). "Metabolic syndrome creates a systemic inflammatory environment characterized by elevated C-reactive protein, tumor necrosis factor-alpha, and interleukin-6 levels that can impair tissue repair processes." (PMID 41226877, 2025). "Parallel epidemiologic data indicate that individuals with higher interleukin-6 (IL-6) and lower IGF-1 levels face an elevated risk of metabolic syndrome." (PMID 41393761, 2025). "Multiple preclinical studies demonstrate that kefir administration reduces pro-inflammatory cytokine levels, including TNF-α, IL-1β, and IL-6, in rodent models of metabolic syndrome." (PMID 40565686, 2025). "This study focused on intermediate outcomes, including dyslipidemia and oxidative stress, and inflammation markers, such as TNF-α, IL-6, and CRP, which predict cardiovascular health risk." (PMID 39840146, 2025). "Hepatic steatosis can stimulate Kupffer cells to release inflammatory cytokines such as tumor necrosis factor-alpha (TNF-α) and interleukin-6 (IL-6), thus creating a vicious cycle that exacerbates both IR and dyslipidemia." (PMID 40927334, 2025). "Adipose tissue, through cytokine secretion, sustains systemic inflammation—a hallmark of metabolic syndrome—further aggravated by neutrophil elastase activity and rhythmic macrophage secretion of Tumor Necrosis Factor Alpha (TNF-α) and interleukin-6 (IL-6)." (PMID 41303617, 2025). "Its levels rise with the number of metabolic syndrome components, largely due to adipocyte-driven low-grade inflammation and IL-6–mediated stimulation of hepatic hepcidin synthesis." (PMID 41156458, 2025). "Inflammatory mediators such as TNF-α and IL-6 amplify oxidative stress and vascular injury, while dyslipidemia accelerates atherogenesis." (PMID 41227114, 2025). "Conversely, a meta-analysis on aerobic, resistance, and combined training in patients with metabolic syndrome reported increases in IL-6 and IL-10 levels following the combined regimen." (PMID 40219022, 2025). "Tocilizumab, a humanized monoclonal antibody that targets both the soluble and membranous forms of interleukin-6 (IL-6) receptor, exacerbates dyslipidemia by blocking IL-6 signaling and inducing apolipoprotein expression in the liver." (PMID 40526615, 2025). "In this context, BLE reduced oxidative stress and levels of TNF-α, IL-6 and IL-10 in the muscles of rats with metabolic syndrome." (PMID 38257152, 2024).
metabolic syndrome (continued). "Recent studies also showed that dyslipidemia was related to higher levels of inflammatory markers, such as interleukin-6 (IL-6), tumor necrosis factor alpha-a (TNF-α), and C-reactive protein (CRP)." (PMID 38566090, 2024). "Previous results from our research group demonstrated, in the genetic model of metabolic syndrome (Zucker rat), that increased NA has an inhibitory role in the release of IL-1β and stimulates the release of IL-6 by peritoneal macrophages." (PMID 39064652, 2024). "Inflammation is believed to be a driver of metabolic syndrome, with the condition displaying enhanced secretion of pro-inflammatory cytokines (e.g., interleukin-6; IL-6, and tumour necrosis factor α; TNFα) from adipose tissue and leukocytes." (PMID 38671852, 2024). "Spexin treatment has shown to inhibit inflammation by reducing blood IL-6 level in a metabolic syndrome rat model induced by high-fructose diet and blocking macrophage recruitment to adipose tissue in an obese mouse model." (PMID 38919263, 2024). "Although IL-6 theoretically has the potential to regulate metabolism, adverse effects such as dyslipidemia have been observed with IL-6 inhibitors (e.g., TCZ) in clinical trials." (PMID 39749325, 2024). "The importance of proinflammatory cytokines like IL-6 has been documented to alter the blood lipid profile, signifying the importance of inflammation in dyslipidemia." (PMID 38275648, 2024). "Persistent low-grade inflammation, marked by elevated levels of inflammatory markers such as C-reactive protein (CRP) and interleukin-6 (IL-6), is common in individuals with metabolic syndrome." (PMID 39574946, 2024). "The potent inflammatory cytokines TNF-a and IL-6 are involved in the development of metabolic syndrome and insulin resistance." (PMID 39767248, 2024). "This process also involves the release of chemokines and pro-inflammatory cytokines (e.g., tumor necrosis factor (TNF)-α, interleukin (IL)-1β, and IL-6), which contribute to and promote systemic inflammation and metabolic syndrome." (PMID 39497804, 2024). "Specific genetic variations: Genetic variations in genes such as TGFB1, IL6, and TLR4 are associated with a higher probability of adverse effects and metabolic syndrome." (PMID 39246917, 2024). "Significant higher values were found for anthropometric variables and markers of glucose and dyslipidemia in individuals with higher BMI, as well as elevated levels of C-reactive protein, fibrinogen, IL-6, uric acid, and D-dimer." (PMID 39081294, 2024). "Herein, it was perceived that Raydel OSO inhibits the IL-6 production, which consequently amends dyslipidemia, precisely elevating HDL level." (PMID 37627620, 2023). "IL1β, IL6 and TNFa are highly expressed in metabolic syndrome, and their expression levels are down-regulated after exercise." (PMID 37053002, 2023). "T2DM and metabolic syndrome are associated with a chronic state of low-grade inflammation, with increased serum levels of CRP and pro-inflammatory cytokines, such as IL-6, IL-1β and TNF-α." (PMID 38140319, 2023). "All subjects with urolithiasis and metabolic syndrome were characterized by significantly higher inflammatory markers IL-6 and TNF-α, as confirmed in the literature." (PMID 36830821, 2023). "Growing evidence suggests that the consumption of TFAs is associated with dyslipidemia and the activation of systemic inflammatory responses, such as elevated CRP, interleukin-6, and tumor necrosis factor." (PMID 37710270, 2023). "In patients with metabolic syndrome, increased serum levels of IL-6 and TNF-α have been found to be associated with the severity of metabolic syndrome development." (PMID 37796781, 2023). "Researchers also found a significant relationship between isoleucine and IL-6 in patients with metabolic syndrome, suggesting isoleucine is a potential predictive biomarker of the pro-inflammatory state of nascent metabolic syndrome." (PMID 37762992, 2023).
metabolic syndrome (continued). "in ameliorating liver function and dyslipidemia to suppress interleukin-6 by increasing HDL functionality in the ethanol-induced hepatic injury zebrafish model." (PMID 38136235, 2023). "Researchers found that IL-6 measured 9–16 years postpartum in women with a history of early-onset preeclampsia relates to metabolic syndrome features such as waist circumference, BMI, fasting triglycerides, and fasting HDL cholesterol." (PMID 37887854, 2023). "Chronic inflammation has been extensively studied as a component of the metabolic syndrome due to the release of pro-inflammatory adipokines, such as leptin, interleukin-6 (IL-6), tumor necrosis factor-α (TNFα), and others, by adipose tissue." (PMID 37957462, 2023). "The associations between the subgroup of patients grouped by PaO2/FiO2 ratio and the administration of IL-6 blocker treatment (p = 0.04, Chi-squared test) metabolic syndrome (p = 0.03, Chi-squared test) were statistically significant." (PMID 37893011, 2023). "The study also showed an association between patients with arterial hypertension and dyslipidemia and an increased expression of vWF/CTNNB-1 (p = 0.049/p = 0.023) and IL-6/GJA-1 (p = 0.034/p = 0.004), respectively." (PMID 36992415, 2023). "L. reuteri V3401 supplementation in individuals with metabolic syndrome reduced IL-6 and soluble vascular cell adhesion molecule 1 and increased the amount of Verrucomicrobia." (PMID 36674680, 2023). "Higher parity has been associated with increases in some inflammatory markers (fibrinogen, D-dimer, GlycA, high-sensitivity C-reactive protein, and interleukin-6 levels), which reflect increased risks of cardiovascular diseases and metabolic syndrome." (PMID 37937292, 2023). "Alcohol-induced dyslipidemia, especially lower HDL-C and higher TG, is linked to an elevation of inflammatory cytokines, such as IL-6." (PMID 36671520, 2023). "LPS, ROS, MDA, and Keap1 were significantly positively correlated with inflammatory cytokines (IL-1β, COX2, TNF-α, IL-6, and iNOS), metabolic syndrome (LDL-C, T-CHO, TG, and BUN), ABW, and ADG at 45 d, 60 d, and 90 d of sample collection." (PMID 38003191, 2023). "In acute inflammation, such as that caused by accidental injury, and chronic inflammation, such as that caused by metabolic syndrome and cancer, vascular endothelial cells express pro-inflammatory and thrombus-promoting factors such as VWF, TF, and IL-6." (PMID 35200650, 2022). "The mean levels of serum Il-6/TNF-a/MCP-1 were significantly higher in all the types of dyslipidemia among male participants." (PMID 36032093, 2022). "Female participants with all types of dyslipidemia but low HDL-C showed an elevation of IL-6 and MCP-1 levels, and those with dyslipidemias and hypercholesterolemia presented higher levels of TNF-a compared to the normal participants." (PMID 36032093, 2022). "IL‐6 and IL‐10 are markers of both IBD and metabolic syndrome and can cause inflammation in the colon if continuously being produced." (PMID 35189037, 2022). "Patients with metabolic syndrome have elevated serum levels of proinflammatory mediators such as tumor necrosis factor-alpha interleukin-6 and C-reactive protein." (PMID 36361416, 2022). "Inflammatory markers that have been associated with metabolic syndrome are hs-CRP, TNF-α, fibrinogen, and IL-6." (PMID 35736651, 2022). "Another suggested explanation is that dyslipidemia is mediated by the direct effect of IL-6 levels, raised through the blockage of IL-6R on administering tocilizumab." (PMID 36675722, 2022). "Plasma levels of IL-6 and IL-18 were significantly higher in our group of patients with dyslipidemia and confirmed the presence of unstable atherosclerotic plaque compared to in the healthy control group." (PMID 35630041, 2022). "OA and the metabolic syndrome are recognized as the low-grade inflammatory condition with elevations in systemic inflammatory mediators such as interleukin-1 (IL-1), interleukin-6 (IL-6), and tumor necrosis factor (TNF)." (PMID 36175967, 2022).